KRT6A (keratin 6A)
Diseases named in the same sentence as KRT6A in open-access papers (continued):
Sharing a sentence is not in itself a finding about the gene and the disease.
adenocarcinoma (8 papers, 2014 to 2025). A common cancer characterized by the presence of malignant glandular cells. "Three genes (DSC3, KRT6A and DMRT2) were predicted as targets of miR-375, the miRNA upregulated in adenocarcinoma, and these genes were consistently down-regulated in this histological subtype." (PMID 24625834, 2014). "Then, by staining for squamous epithelium markers (including KRT5, KRT6A, SFN, and KRT14) and columnar epithelium markers (including EPCAM and KRT8), groups 3, 7, and 10 were identified as squamous cancer cells, and groups 5, 6, and 8 were identified as adenocarcinoma cells." (PMID 36052088, 2022).
KRT6A also shares sentences with these, for which no sentence is quoted: Palmoplantar keratoderma (5 papers); lung squamous cell carcinoma (4); colorectal cancer (3); asthma (2); atopic dermatitis (2); epidermolysis bullosa simplex (2); epidermolytic hyperkeratosis (2); lymph node metastasis (2); Nail dystrophy (2); renal carcinoma (2); skin disorder (2); adenocarcinoma of gallbladder (1); autosomal recessive congenital ichthyosis (1); bladder urothelial carcinoma (1); breast tumors (1); cholesteatoma (1); chronic periodontitis (1); contact dermatitis (1); cutaneous melanoma (1); Dent Disease 2 (1); Dowling-Degos disease (1); dyskeratosis congenita (1); ectodermal dysplasia (1); epidermolytic ichthyosis (1); epidermolytic palmoplantar keratoderma (1); gallbladder cancer (1); genetic disorder (1); genodermatosis (1); hyperplasia (1); ichthyosis (1).
A further 24 diseases each share a sentence with KRT6A in 1 paper.